SLC34A3 (solute carrier family 34 member 3)
Diseases named in the same sentence as SLC34A3 in open-access papers:
SLC34A3 is named in the same sentence as 36 diseases in open-access papers, as found by Europe PMC text mining. Sharing a sentence is not in itself a finding about the gene and the disease. The quoted sentences say what the papers report.
Hypercalciuria (34 papers, 2010 to 2025). "Previous studies have suggested that patients heterozygous for SLC34A3 pathogenic variants have a milder phenotype that includes borderline-low serum phosphate levels, hypercalciuria, and NC." (PMID 40428323, 2025). "We also detected a monoallelic pathogenic variant of SLC34A3 in an 18-year-old male who had borderline serum phosphorus, hypercalciuria, normal kidney function, and nephrocalcinosis." (PMID 40428323, 2025). "Hypophosphatemic rickets with hypercalciuria (OMIM phenotype number 241530) is an AR condition due to inactivating variants in SLC34A3, resulting in loss of NPT2c activity and subsequent renal phosphorus wasting with hypophosphatemia." (PMID 38606357, 2024). "Biallelic pathogenic variants in the SLC34A3 gene, encoding for the NPT2c cotransporter, cause Hereditary Hypophosphatemic Rickets with Hypercalciuria (HHRH)." (PMID 36596813, 2023). "This was used in patients with mutations of CYP24A1 and SLC34A3 gene, leading to persistently raised 1,25-dihydroxyvitamin D, hypercalcemia, hypercalciuria, and nephrocalcinosis/nephrolithiasis." (PMID 37274338, 2023). "Mutations in SLC34A3 encoding the renal phosphate transporter NPT2c have been associated with autosomal recessive hypophosphatemic rickets (ARHR) with hypercalciuria (MIM 241530)." (PMID 34721296, 2021). "Hereditary hypophosphatemic rickets with hypercalciuria results from the loss of function mutations in the SLC34A3 gene that encodes NaPi-2c, with consequent tubular Pi wasting and hypophosphatemia." (PMID 34199067, 2021). "Homozygous or compound heterozygous mutations involving SLC34A3 have been associated with hereditary hypophosphatemic rickets with hypercalciuria (HHRH, MIM: 241530; Mejia‐Gaviria, Gil‐Peña, Coto, Pérez‐Menéndez, & Santos, 2010)." (PMID 32155322, 2020). "Most recently, heterozygous mutations of the SLC34A3 gene have been identified in individuals with milder clinical symptoms, including isolated hypercalciuria, mild hypophosphatemia, and elevated 1,25‐dihydroxy vitamin D [1,25‐(OH) 2 D]." (PMID 32155322, 2020). "If the hypercalciuria occurred before treatment, it is possible that SLC34A3 mutation caused hypercalciuria, with the simultaneously found hypophosphatemia and hypercalciuria." (PMID 32155322, 2020). "Loss of function in the third member of the sodium phosphate cotransporter family type II (NaPi-IIc/NPT2c) which is encoded by the SLC34A3 gene causes hereditary hypophosphatemic rickets with hypercalciuria (HHRH)." (PMID 29809158, 2018). "Hereditary hypophosphatemic rickets with hypercalciuria is caused by loss-of-function in the type 2c sodium phosphate cotransporter encoded by the SLC34A3 gene." (PMID 20074341, 2010). "Non-FGF23 mediated forms of hypophosphatemic rickets include autosomal recessive hereditary hypophosphatemic rickets with hypercalciuria secondary to biallelic variants in the solute carrier family 34-member 3 (SLC34A3) gene encoding the sodium-dependent phosphate transport protein 2C." (PMID 41445557, 2025). "Data suggests that carriers (heterozygotes) of inactivating variants in SLC34A3 may have increased risk of NL, NC, hypercalciuria, and hypophosphatemia." (PMID 38606357, 2024). "Similarly, carriers of rare variants in SLC34A3 showed lower phosphate levels and higher odds of urolithiasis, consistent with phenotypes of patients affected by hypophosphatemic rickets with hypercalciuria due to recessive SLC34A3 mutations (MIM #241530)." (PMID 36890159, 2023). "Mutations in SLC34A3 can cause hereditary hypophosphatemic rickets with hypercalciuria." (PMID 35240026, 2022). "In view of these points, we speculated that the heterozygous variant of SLC34A3 may be the cause for the hypercalciuria in this family." (PMID 32155322, 2020). "SLC34A3 is the cause gene of hypophosphatemic rickets with hypercalciuria, and heterozygous carriers may have milder clinical symptoms." (PMID 32155322, 2020).
Hypercalciuria (continued). "Two cases had SLC34A3 mutations that lead to hereditary HR with hypercalciuria." (PMID 31514490, 2020). "Another autosomal recessive form of hypophosphatemic rickets caused by SLC34A3 mutations, is hereditary hypophosphatemic rickets with hypercalciuria (HHRH) distinguished by hypercalciuria and response to phosphate alone." (PMID 41375889, 2025). "Biallelic loss-of-function variants in SLC34A1 and SLC34A3 cause two rare phosphate-wasting tubulopathies: idiopathic infantile hypercalcemia (IIH) and hereditary hypophosphatemic rickets with hypercalciuria, respectively." (PMID 40943461, 2025). "Hereditary hypophosphatemic rickets with hypercalciuria (HHRH; #241530) is an autosomal recessive disorder caused by biallelic pathogenic variants of the SLC34A3 gene, and characterized by phosphaturia, low TMP/GFR, and high 1,25(OH)2D concentrations." (PMID 41008628, 2025). "Genetic causes of renal phosphate wasting with hypercalciuria and NL and/or NC are due to variants in SCL34A1, SLC34A3, and SLC9A3R1." (PMID 38606357, 2024). "Hypophosphatemic rickets with hypercalciuria, HHRH (MIM # 241530) is an autosomal recessive disease caused due to biallelic variants in SLC34A3 (solute carrier family 34, member 3)." (PMID 36692815, 2023). "We observed typical HVD biochemical features in SLC34A3 relatives’ group, namely hypercalciuria in 8/11 cases, low serum PTH in 6/11 cases, high 1,25-(OH)2D in 9/11 cases." (PMID 34721296, 2021). "The hereditary hypophosphatemic rickets with hypercalciuria is characterized bymutations in the gene of the sodium and phosphorus co-transporters (SLC34A3), whichleads to severe dysfunctions in the NaPi-IIa co-transporter." (PMID 29617471, 2018). "However, many SLC34A1 and SLC34A3 monoallelic carriers appear to have a lower TmP/GFR, elevated calcitriol levels, hypercalciuria, and a higher risk to develop kidney stones than the general population [61▪▪,62]." (PMID 40357590, 2025). "Increased renal phosphate wasting, mild hypophosphatemia, increased 1,25(OH)2D and hypercalciuria without metabolic bone disease, can be present in patients with heterozygous SLC34A3 mutations, indicating haploinsufficiency." (PMID 29280738, 2017). "Hereditary HR with hypercalciuria (HHRH, MIM 241530) is an autosomal recessive disease caused by inactivating mutations in the SLC34A3 (solute carrier family 34, member 3, also known as NaPi-2c, MIM 609826)." (PMID 29280738, 2017). "Loss-of-function variants in SLC34A1 and SLC34A3 are the cause of two rare phosphate-wasting disorders, idiopathic infantile hypercalcemia type 2 (IIH, OMIM #616963) and hereditary hypophosphatemic rickets with hypercalciuria (HHRH, OMIM #241530), respectively." (PMID 40943461, 2025). "Hypophosphatemic rickets with hypercalciuria arises from SLC34A3 gene anomalies, inducing phosphate excretion and hypercalciuria; VUS in SLC34A3 were identified in 4% of patients." (PMID 40126616, 2025). "Both groups of patients, with SLC34A1 or SLC34A3 defects, shared a common biochemical pattern, including elevated 1,25(OH)2D and alkaline phosphatase levels, suppressed parathyroid hormone (PTH), and hypercalciuria." (PMID 41008628, 2025).
hypophosphatemia (23 papers, 2014 to 2025). Lower than normal levels of phosphates in the circulating blood. "Not in all patients with biallelic pathogenic variants in SLC34A1 and SLC34A3 can hypophosphatemia be observed." (PMID 41008628, 2025). "The patient’s father carried both the SLC34A1 and SLC34A3 mutations in heterozygosis, he had hypophosphatemia but was asymptomatic." (PMID 40943461, 2025). "Seven patients diagnosed with hypercalcemia had a variant in heterozygous state in genes associated with hypophosphatemia (SLC34A3, SLC34A1, and SLC9A3R1 genes)." (PMID 38586466, 2024). "In contrast, inactivating mutations in SLC34A1 or SLC34A3 in humans are both associated with hypophosphatemia and nephrolithiasis." (PMID 34071837, 2021). "SLC34A3 plays a role in phosphate reabsorption in the kidney and its mutation results in increased renal phosphate loss and subsequent hypophosphatemia." (PMID 29280738, 2017). "In contrast, patients affected with biallelic SLC34A3 variants presented in childhood or even adulthood with rickets/osteomalacia and/or osteopenia/osteoporosis, hypophosphatemia, and, less frequently, nephrocalcinosis, while the prevalence of kidney stones was comparable." (PMID 41008628, 2025). "In our cohort, only 2 patients with biallelic variations in SLC34A3 (class V) or SLC34A1 (class III) presented with hypophosphatemia." (PMID 34721296, 2021). "Hypophosphatemia (serum phosphate Z-score < -2) was reported in 7 patients (27-28%) with CYP24A1 biallelic mutations and 1 patient with SLC34A3 biallelic mutations." (PMID 34721296, 2021). "The recent study of a family who displayed heterozygous inactivating mutations of SLC34A1 and SLC34A3 with severe hypophosphatemia and rickets supports the synergic and non-redundant action of SLC34A1 and SLC34A3 on renal phosphate transport." (PMID 34071837, 2021).
hypophosphatemic rickets (16 papers, 2018 to 2025). Rickets due to low serum phosphate concentrations, the cause of which can be nutritional or genetic. "Five participants with SLC34A3 variants and 3 with other variants associated with other forms of hypophosphatemic rickets completed 24-hour urine collections." (PMID 41021020, 2025). "24-hour urine parameters demonstrated clinically meaningful differences in urine volume, calcium, and phosphate between those who harbored SLC34A3 variants and those with other genetic variants associated with hypophosphatemic rickets." (PMID 41021020, 2025). "Such a digenic mechanism, with both heterozygous SLC34A1 and SLC34A3 mutations, has been postulated as the cause of hypophosphatemic rickets with renal stone disease in an American family." (PMID 34721296, 2021). "Interestingly, 10 (67%) patients had variants associated with hypophosphatemic rickets, of which 60% harbored SLC34A3 variants associated with autosomal recessive HHRH." (PMID 41021020, 2025). "In contrast, enthesopathy is not described in FGF23-independent forms of hypophosphatemic rickets, such as hereditary hypophosphatemic rickets with hypercalciuria due to pathogenic variants in SLC34A3, which encodes the renal tubular NPT2 phosphate transporter." (PMID 37871131, 2024).
nephrolithiasis (15 papers, 2017 to 2025). The presence of a calculus in the pelvis of the kidney; this is most often composed of mineral salts and proteins. "A number of studies have suggested that heterozygous carriers of pathogenic SLC34A3 have higher rates of nephrolithiasis and nephrocalcinosis with an approximately 3-fold increased risk compared to the general population." (PMID 41021020, 2025). "Monoallelic SLC34A3 variants likely increase kidney stone risk via effects that are insufficient to cause fully penetrant Mendelian disease but confer a higher risk than aggregate effects of known common risk alleles." (PMID 40372791, 2025). "Both IIH and HHRH were originally described as autosomal-recessive disorders; however, heterozygous mutations in SLC34A1 and SLC34A3 seem to be associated with an increased risk to develop nephrolithiasis in adults." (PMID 40943461, 2025). "We describe here a group of patients with recurrent nephrolithiasis for whom genetic exploration revealed variants in the SLC34A3 gene that codes for NPT2c protein." (PMID 36596813, 2023). "We studied 20 patients with recurrent nephrolithiasis and low serum phosphate concentration harboring variants in the SLC34A3 gene." (PMID 36596813, 2023). "Upon genetic analysis of 670 individuals with various types of kidney stones, we identified two more patients with heterozygous SLC34A3 c.575C>T, p.Ser192Leu mutations." (PMID 30798342, 2019). "Clinically, HHRH patients, who carry homozygous or compound heterozygous SLC34A3/NPT2c mutations, often show hypophosphatemia following decreased renal phosphate reabsorption, rickets and/or osteomalacia and frequently kidney stones or nephrocalcinosis." (PMID 29809158, 2018). "Homozygote and heterozygote mutations in the SLC34A3 gene were found to lead to a significantly increased risk of kidney stone formation and bone deformities which in turn led to short stature and growth delay." (PMID 29809158, 2018). "Homozygote and heterozygote mutations in the SLC34A3 gene lead to a significantly increased risk of kidney stone formation and bone deformities, compared with healthy controls." (PMID 29809158, 2018). "Patient 4, with nephrolithiasis at presentation and a SLC34A3 mutation, had a normal renal ultrasound at the last follow up, after treatment with a low salt diet, phosphate and citrate supplementation, and thiazide diuretics; urologic intervention was not required." (PMID 34858904, 2021). "Finding of variants in the genes SLC34A1, SLC34A3 and SLC9A3R1 is not uncommon in patients with renal phosphate leak and kidney stones." (PMID 36596813, 2023).
rickets (13 papers, 2011 to 2025). Bone softening and weakening usually caused by deficiency or impaired metabolism of vitamin D. Deficiency of calcium, magnesium, or phosphorus may also cause rickets. "However, subsequent studies of patients harboring SLC34A3 biallelic pathogenic variants showed a large diversity of the phenotype, low serum phosphate concentration and rickets being inconstant." (PMID 36596813, 2023). "In previous studies, phenotypic heterogeneity was found in patients with SLC34A3 variants: approximately 25% of HHRH patients did not exhibit rickets and half lacked renal calcification." (PMID 35842615, 2022). "However, we also found variants in genes associated with primary hyperparathyroidism (GCM2), renal hypophosphatemia with or without rickets (SLC34A1, SLC34A3, SLC9A3R1, VDR, and CYP27B1), DiGeorge syndrome (TBX1 and NEBL), and hypophosphatasia (ALPL)." (PMID 38586466, 2024).
nephrocalcinosis (11 papers, 2017 to 2025). Nephrocalcinosis is a disorder that occurs when too much calcium is deposited in the kidneys. "In recessive disorders homozygous mutations are helpful to assess the clinical impact of a certain genetic variant as exemplified here by a young adult with nephrocalcinosis due to a homozygous SLC34A3 c.575C > T, p.Ser192Leu mutation." (PMID 30798342, 2019). "In patients with nephrocalcinosis (n=55; 44 children and 11 adults), we identified 18 (33%) patients with biallelic class IV or V variations, mostly in CYP24A1 (n=25/28) and also in SLC34A3 (n=3/28); 4 adults with biallelic CYP24A1 mutations presented chronic kidney disease (CKD-EPI<60mL/min)." (PMID 34721296, 2021). "Mutations in a heterozygous state were found in patients with renal stones (n=6), nephrocalcinosis (n=4) and no renal complications (n=5), mostly in CYP24A1 (n=9) and SLC34A3 (n=5)." (PMID 34721296, 2021).
hereditary hypophosphatemic rickets with hypercalciuria (7 papers, 2018 to 2025). Hereditary hypophosphatemic rickets with hypercalciuria (HHRH) is a hereditary renal phosphate-wasting disorder characterized by hypophosphatemia and hypercalciuria associated with rickets and/or osteomalacia. "Loss-of-function mutations of SLC34A3 represent an established cause of a distinct renal phosphate wasting disorder termed hereditary hypophosphatemic rickets with hypercalciuria (HHRH)." (PMID 30798342, 2019).
Hypercalcemia (7 papers, 2021 to 2025). An abnormally increased calcium concentration in the blood. "Specifically, systemic calcitriol levels can directly affect intestinal mineral absorption processes, e.g., by regulating SLC34A3 and TRPV6 expression, which are counterbalanced at the local level by calcitriol elimination to prevent hypercalcemia in L animals." (PMID 36005601, 2022). "Mutations in SLC34A3 and SLC9A3R1 have been associated with phosphate wasting without hypercalcemia." (PMID 34721296, 2021). "Mutations in SLC34A3 are responsible for ARHR, with characteristic high urine calcium and serum 1,25-(OH)2D, but hypercalcemia in these patients was not documented to date." (PMID 34721296, 2021). "We recommended studying the genes associated with genetic rickets (SLC34A1, SLC34A3, and SLC9A3R1) in those patients with hypercalcemia of suspected genetic cause but without a confirmatory genetic diagnosis, because they could have a heterozygous pathogenic variant." (PMID 38586466, 2024).
autosomal recessive hypophosphatemic rickets (3 papers, 2021 to 2025). Autosomal recessive hypophosphatemic rickets (ARHR) is a hereditary renal phosphate-wasting disorder characterized by hypophosphatemia, rickets and/or osteomalacia and slow growth. "Autosomal dominant hypophosphatemic rickets is due to FGF23 variants, while autosomal recessive hypophosphatemic rickets is due to biallelic variants in DMP1, ENPP1, FAM20C or SLC34A3." (PMID 40533633, 2025).
cystinuria (2 papers, 2025). Cystinuria is a renal tubular amino acid transport disorder characterized by recurrent formation of kidneys cystine stones. "In our cohort, SLC34A3 abnormal variants were detected in four patients, being the second most common after cystinuria." (PMID 40428323, 2025).
idiopathic hypercalciuria (2 papers, 2020 to 2021). A rare renal disease characterized by persistent excess urinary calcium excretion in the absence of an underlying systemic disease and hypercalcemia. "Furthermore, two patients with idiopathic hypercalciuria without bone signs and biallelic variations in SLC34A3 were described suggesting a potential role of SLC34A3 in HVD phenotype." (PMID 34721296, 2021).
osteoporosis (2 papers, 2018 to 2024). A condition of reduced bone mass, with decreased cortical thickness and a decrease in the number and size of the trabeculae of cancellous bone (but normal chemical composition), resulting in increased fracture incidence. "Genetic counseling and screening for SLC34A3 mutations can be helpful in adult onset phenotype with unexplained osteoporosis, bone deformities and especial recurrent renal stones." (PMID 29809158, 2018).
urolithiasis (2 papers, 2023). Stone(s) within the urinary tract. "In order to better understand the responsibility of SLC34A3 pathogenic variants in the phenotype of patients with renal phosphate leak or recurrent urolithiasis, the aim of the present study was to analyze the consequences of 13 identified SLC34A3 variants on NPT2c phosphate transport capacity." (PMID 36596813, 2023).
autosomal recessive disease (2 papers, 2012 to 2018). Autosomal recessive form of disease. "HHRH is an autosomal recessive disease and our patient in this study was homozygous for SLC34A3 gene mutation, therefore, this patient must have inherited the mutation from both parents for complete disease manifestations." (PMID 22672866, 2012). "Since HHRH is an autosomal recessive disease, biallelic mutations are required for full-scale disease manifestations; loss of one SLC34A3 allele does not always lead to laboratory abnormalities." (PMID 29809158, 2018).
SLC34A3 also shares sentences with these, for which no sentence is quoted: hereditary hypophosphatemic rickets (4 papers); autosomal dominant hypophosphatemic rickets (2); hyperphosphatemia (2); osteomalacia (2); tumor (2); X-linked dominant hypophosphatemic rickets (2); Barakat syndrome (1); calcification (1); chronic kidney disease (1); DiGeorge syndrome (1); Failure to thrive (1); Fanconi syndrome (1); genetic diseases (1); hypophosphatasia (1); idiopathic infantile hypercalcemia (1); osteopetrosis (1); primary hyperoxaluria type 3 (1); primary hyperparathyroidism (1); renal disease (1); renal tubular acidosis (1); X-linked recessive hypophosphatemic rickets (1); xanthinuria type I (1).